FGFR3 (fibroblast growth factor receptor 3)
Diseases named in the same sentence as FGFR3 in open-access papers (continued):
Sharing a sentence is not in itself a finding about the gene and the disease.
postmenopausal osteoporosis (2 papers, 2023). Metabolic disorder associated with fractures of the femoral neck, vertebrae, and distal forearm. "The optimal timing and duration of administrating FGFR3 inhibitors may be considered during DO to develop treatment strategies of fracture healing associated with postmenopausal osteoporosis." (PMID 36927417, 2023). "Activated FGFR3 suppresses the ability of bone regeneration and bone mineralization in a mouse model of postmenopausal osteoporosis." (PMID 36927417, 2023). "A study on postmenopausal osteoporosis mice showed that FGFR3 activation inhibited the ability of bone regeneration and bone mineralization." (PMID 37108419, 2023). "This study aimed to assess the influence of FGFR3 signaling on the ability of bone regeneration and bone mineralization during menopause using a mouse model of DO mimicking postmenopausal osteoporosis." (PMID 36927417, 2023). "An in vitro study of osteoclast function may accurately assess the impact of meclozine on activated FGFR3 signaling in postmenopausal osteoporosis." (PMID 36927417, 2023). "FGFR3 signaling can be a potential therapeutic target in patients with postmenopausal osteoporosis." (PMID 36927417, 2023). "Thus, FGFR3 signaling could be a potential therapeutic target for patients with postmenopausal osteoporosis." (PMID 36927417, 2023).
RASopathy (2 papers, 2021 to 2022). Developmental syndromes caused by germline mutations (or in rare cases by somatic mosaicism) in genes that alter the Ras subfamily and mitogen-activated protein kinases that control signal transduction. "As expected, RAS proteins are the ones with the highest number of associations, although RASopathies related to SPRED1, MEK1/2, PTPN11, FGFR3 and SPRY1 may regulate RAS signaling differently, affecting primarily the classical RAS versus RRAS signaling." (PMID 34229750, 2021). "FGFR3 directly interacts with RAS, and our results suggest that 24% of its interactome is shared with other RASopathy proteins." (PMID 34229750, 2021). "FGFR3 was considered responsible for mosaic RASopathies, but has not been included in any RASopathy protein panel yet in clinical studies." (PMID 34229750, 2021). "Interestingly, FGFR3 did show direct interaction with RAS, was previously shown to exert and impact on RAS-MAPK signaling pathway and had an interactome overlap of 24% with other RASopathy protein neighbors." (PMID 34229750, 2021).
rickets (2 papers, 2023 to 2024). Bone softening and weakening usually caused by deficiency or impaired metabolism of vitamin D. Deficiency of calcium, magnesium, or phosphorus may also cause rickets. "X-linked dominant hypophosphatemic rickets, XLDHR (MIM # 307800) belongs to the FGFR3-dependent rickets category, and it is caused by pathogenic variants in PHEX (phosphate-regulating endopeptidase homolog X-linked)." (PMID 36692815, 2023). "These molecular defects cause abnormal functions of the cartilage extracellular matrix (COMP), paracrine signalling factors (PHEX, FGFR3-related rickets), transcriptional regulation (LZTR1), histone methylation (KMT2A), posttranslational modification (NAA15), and mtDNA replication and repair (POLG)." (PMID 39415983, 2024).
sinonasal carcinomas (2 papers, 2021 to 2025). "Except for the nasopharyngeal tumors and the multiphenotypic sinonasal carcinomas, the vast majority of FGFR3::TACC3-positive reported cases were supposed to have represented SCC." (PMID 39387893, 2025).
Sjögren syndrome (2 papers, 2023 to 2025). "Regarding the SN group, most patients had underlying immune-mediated mechanisms: Sjögren syndrome (n = 4), autoimmune hepatitis (n = 3), systemic lupus erythematosus (n = 1), and FGFR3-related (n = 5)." (PMID 37793400, 2023). "One noteworthy finding of this study is that the presence of anti‐AGO or anti‐FGFR3 antibodies, which clinically delineate subgroups of SNN or associate with autoimmune conditions like Sjögren's syndrome, did not correlate with any distinctive cytokine profile." (PMID 40037793, 2025).
small cell neuroendocrine carcinoma (2 papers, 2024 to 2025).
Small Fiber Neuropathy (2 papers, 2025 to 2026). "Autoantibodies against fibroblast growth factor receptor 3 (FGFR3) have been suggested as a diagnostic marker in both sensory large and small fiber neuropathy." (PMID 41142778, 2025).
spermatocytic seminoma (2 papers, 2011 to 2012). A rare variant of seminoma characterized by the presence of three cell types: round cells with eosinophilic cytoplasm, small cells with dark nucleus and a small amount of cytoplasm, and mono-or multinucleated giant cells. "However, activating mutations in FGFR3 have been linked to the formation of spermatocytic seminomas." (PMID 21674058, 2011). "Indeed, functionally related mutations of FGFR3 and HRAS were identified in spermatocytic seminoma, a rare testicular tumour distinct from more common seminomatous and non-seminomatous neoplasms." (PMID 22879958, 2012).
synovial sarcoma (2 papers, 2021 to 2023). "Stimulation of human synovial sarcoma cell line HS-SY-II with recombinant FGF18 protein increased the dependence of the cells on FGF18 and enhanced the phosphorylation levels of ERK, P38 and FGFR3 proteins in human synovial sarcoma cell line HS-SY-II." (PMID 37228502, 2023). "Thus, exogenous FGF18 promotes synovial sarcoma growth through FGFR3 and ERK pathways in synovial sarcoma cell lines." (PMID 37228502, 2023). "Changes in TERT-related pathways, such as gene amplifications in dedifferentiated liposarcomas (DDLPS) or FGFR3 activation in synovial sarcomas (SS), likely promote telomerase-mediated telomere maintenance." (PMID 33924498, 2021).
testis tumor (2 papers, 2020 to 2024). "FGFR3, which has a role in testis tumor development might be coregulated by a different set, SFPQ, FXR2, and HNRNPA1, and all three bind it based on POSTAR2." (PMID 32316190, 2020).
thymic carcinoma (2 papers, 2017 to 2022). Thymic carcinoma (TC) is a type of thymic epithelial neoplasm characterized by a high malignant potential. "Motivated by the two thymic carcinomas with an FGFR3 mutation and the one carcinoma with an ALK mutation, we also performed FISH for these two genes." (PMID 27844328, 2017). "We observed a FGFR3 missense mutation in two thymic carcinomas." (PMID 27844328, 2017). "Thus, inhibition of FGFR3 might represent a novel target in a subset of thymic carcinomas." (PMID 27844328, 2017).
viral infections (2 papers, 2015 to 2021). "We found that molecules like SOX2, FGFR3, and CDKN1B could be more affected by different viruses than other molecules shaping the auditory system, suggesting that cochlear development and production of hair and supporting cells might be disrupted by certain viral infections during embryogenesis." (PMID 33419104, 2021).
vulvar carcinoma (2 papers, 2014 to 2020). "The significance of PIK3CA, FGFR3 and FBXW7 mutations for vulvar carcinogenesis and vulvar cancer patient management remains to elucidated." (PMID 32664330, 2020).
adenocarcinoma of the oesophagus (1 paper, 2021). "Two of 16 (%) patients with adenocarcinoma of the oesophagus were found to have FGFR3 rearrangement by RNA-Seq, while one patient with adenocarcinoma of the gastric antrum had high microsatellite instability (MSI-H)." (PMID 34794033, 2021).
adenoma (1 paper, 2010). A neoplasm arising from the epithelium. "No FGFR3-IIIc was detected in the adenoma cell lines, whereas the highest IIIc/IIIb ratio was found in the H64 brain metastasis-derived cells." (PMID 20234367, 2010).
Adrenal insufficiency (1 paper, 2025). Insufficient production of steroid hormones (primarily cortisol) by the adrenal glands. "No other pathogenic variants were found in genes associated with skeletal dysplasias (e.g., FGFR3, COL1A1), adrenal insufficiency (e.g., NR0B1, STAR), or growth retardation (e.g., IGF1R)." (PMID 41218602, 2025).
ameloblastoma (1 paper, 2013). The most common odontogenic tumor, arising from the epithelial component of the embryonic tooth and usually affecting the molar-ramus region of the mandible or maxilla. "The expression of FGF1, FGF2, FGFR2 and FGFR3 in ameloblastoma was previously reported and it was concluded that FGF1 and FGF2 may contribute to the growth and development of ameloblastoma mediated by their receptors." (PMID 24002438, 2013).
anaplastic ependymoma (1 paper, 2023). Anaplastic ependymoma is a rare, malignant type of ependymoma that most often arises in the supratentorial region of the brain of children and young adults and that manifests with variable symptoms including headaches, nausea, vision impairment, memory loss and difficulty walking. "Notably, synonymous variants found in this tumor were detected in other tumors, such as APC (rs41115) variant in MPE, FGFR3 (rs7688609), PDGFRA (rs1873778), and RET (rs1800861) in anaplastic ependymoma Grade III tumor, a-CPP, and myxo-papillary ependymoma (MPE) tumors." (PMID 37273678, 2023).
autonomic dysfunction (1 paper, 2025). "Amongst the possible biomarkers, autoantibodies seemed to be the most intriguing area of interest and specific markers like TS-HDS/FGFR3 antibodies might be present in SFN patients with autonomic dysfunction, even if their diagnostic value is still uncertain in the literature." (PMID 40005694, 2025).
autosomal recessive primary microcephaly (1 paper, 2019). Autosomal recessive primary microcephaly (MCPH) is a rare genetically heterogeneous disorder of neurogenic brain development characterized by reduced head circumference at birth with no gross anomalies of brain architecture and variable degrees of intellectual impairment. "Mutations in a number of identified genes have been found to underlie autosomal recessive primary microcephaly (MCPH) (e.g., MCPH1, ASPM, CASC5, and WDR62) and thanatophoric dysplasia (FGFR3), a subtype of megalencephaly." (PMID 31338027, 2019).
bladder disorders (1 paper, 2023). "The importance of this continuous gene syndrome in bladder disorders was further supported by the finding of somatic FGFR3 mutations in one 8 years old WHS patient with hematuria and a rare form of myofibroblastic bladder tumor." (PMID 36349425, 2023).
bone sarcoma (1 paper, 2023). A sarcoma that arises from the bone. "In bone sarcomas, MET CNV (n = 5) was the most frequent actionable GAs, followed by IDH1 SNV (n = 4) and FGFR3 SNV (n = 3)." (PMID 37546405, 2023).
bronchopulmonary dysplasia (1 paper, 2014). Bronchopulmonary dysplasia is a chronic respiratory disease that results from complications related to lung injury during the treatment of infant acute respiratory distress syndrome in low-birth-weight premature infants or from abnormal lung development in older infants. "Similar accumulation of mast cell mediators was found in lungs of Fgfr3/4 mutant mice that exhibit Bronchopulmonary Dysplasia (BPD) like pathology and in lungs of children with BPD, suggesting that pulmonary mastocytosis could be a common feature found in diffuse lung developmental conditions." (PMID 24722050, 2014).
cartilaginous tumors (1 paper, 2015). "Our findings also suggest that modulation of FGFR3 and related signaling pathways is a potential therapeutic strategy for treating benign cartilaginous tumors." (PMID 26091072, 2015).
cerebral tumors (1 paper, 2017). "Moderate-to-strong FGFR3 immunostaining was predominantly detected in cerebral tumors as compared to other locations (p < 0.001, Fisher’s exact test)." (PMID 28468611, 2017). "Increased FGFR1 and/or FGFR3 expression was therefore a common characteristic of cerebral tumors." (PMID 28468611, 2017). "In pediatric patients, moderate FGFR3 immunostaining was observed in cerebellar (31%, n = 16) and cerebral (29%, n = 14) tumors and strong FGFR3 staining only in cerebral tumors (21%, n = 14), whereas all the spinal cases (n = 5) were negative for FGFR3 (p = 0.065, Fisher’s exact test)." (PMID 28468611, 2017).
chordoma (1 paper, 2017). Chordomas are rare malignant tumors arising from embryonic remnants of the notochord in axial skeleton. "ULK4, NPR1 and CDKL4 were the top most expressed kinases in the Chor-IN-1 cell line, while FGFR3, KDR and WNK2 were less expressed or absent in Chor-IN-1 cells as compared to the other chordoma lines." (PMID 28835717, 2017).
choroid plexus papilloma (1 paper, 2023). "The HBL tumor of this study exhibited exon 25 and exon 9 mutations in ALK and FGFR3 genes; however, mutations in exon 29 and exon 16 in these two genes were previously reported in an atypical-choroid plexus papilloma (a-CPP) tumor." (PMID 37273678, 2023).
clear cell ovarian cancer (1 paper, 2013). "MiR-99 was reported to mediate down-regulation of mTOR/FGFR3 and suppress tumor growth; miR-100 is known to inhibit mTOR signaling and enhance sensitivity to Everolimus in clear cell ovarian cancer; and mTORC1 was recently reported to regulate miR-1 in skeletal myogenesis." (PMID 24009623, 2013).
COVID-19 (1 paper, 2023). A disease caused by infection with severe acute respiratory syndrome coronavirus 2. "All of the 6 intersected genes have been reported to associate with COVID-19, including FGFR3, TP63, CXCL2, CCL20, IL1B and CXCL8." (PMID 37497545, 2023).
diabetes (1 paper, 2024). "Other diabetes-related genes, such as FGFR3, MTA3, PAK4, and KIF22, had similar results." (PMID 39000600, 2024).
diffuse midline glioma (1 paper, 2024). A diffuse glioma that arises from the midline structures of the central nervous system. "The remaining two patients progressed rapidly—an H3K27M mutant diffuse midline glioma with PDGFRA mutation treated with ponatinib and then regorafenib, and an MB with FGFR3 mutation given pazopanib, ifosfamide and doxorubicin." (PMID 38844796, 2024).
embryonal rhabdomyosarcoma (1 paper, 2009). A poorly circumscribed morphologic variant of rhabdomyosarcoma. "Real-time PCR and immunohistochemical examination revealed that embryonal rhabdomyosarcoma patient biopsy specimens were found to over-express FGFR3." (PMID 19888223, 2009).
ependymal tumor (1 paper, 2017). A group of neoplasms which arise from the ependymal lining of the cerebral ventricles and from the remnants of the central canal of the spinal cord. "Immunohistochemistry was used to investigate FGFR3 expression levels in 108 ependymal tumor samples applied to TMAs." (PMID 28468611, 2017).
esophageal squamous cell carcinoma (1 paper, 2020). Esophageal squamous cell carcinoma (ESCC) is a type of esophageal carcinoma (EC) that can affect any part of the esophagus, but is usually located in the upper or middle third. "The previous studies have suggested that FGFR3 may be of diagnostic value in early carcinoma, and further study of FGFR3 expression in early carcinoma of esophageal squamous cell carcinoma is warranted." (PMID 33381388, 2020). "Studies have shown that that FGFR3 expression promoted tumor cell proliferation immunohistochemical analysis of early esophageal squamous cell carcinoma." (PMID 33381388, 2020). "FGF2 and FGFR3 may be used as prognostic markers of esophageal squamous cell carcinoma." (PMID 33381388, 2020). "In this study, the immunohistochemistry of FGF2, FGFR3, and FGFBP1 was used to further verify the expression of the three proteins in 172 patients with esophageal squamous cell carcinoma (ESCC) who had not received preoperative chemoradiotherapy and its effect on the prognosis of ESCC." (PMID 33381388, 2020).
facial clefting (1 paper, 2019). "FGF18 polymorphisms are associated with facial clefting, FGFR3 mutations cause skeletal dysplasias 35, and Fgf18 deleted mice have delayed chondrocyte differentiation." (PMID 31400222, 2019).
gallbladder carcinoma (1 paper, 2017). "AKT2, FGFR3, and FGF10 amplification had been reported in Chinese gallbladder carcinoma." (PMID 28029662, 2017).
growth (1 paper, 2017). The increase in size or mass of an entire organism, a part of an organism or a cell. "To date, eight different pathogenic mutations of FGFR3 transmembrane segment have been shown implicated in cancer and growth disorders including ACH; however, exact pathogenetic mechanism of the disease is still unclear." (PMID 28679403, 2017).
gynecological cancers (1 paper, 2023). "Therefore, FGFR3 may also become a potential target for patients with gynecological cancers." (PMID 37064128, 2023).
Hyperinsulinemia (1 paper, 2014). An increased concentration of insulin in the blood. "Insulin insensitivity with secondary hyperinsulinemia is uncommonly seen in HCH patients with FGFR3 mutations which may represent a new association." (PMID 25505998, 2014).
hyperphosphatemia (1 paper, 2016). Abnormally high level of phosphate in the blood. "The dose-limiting toxicities due to inhibition of FGFR1/FGFR3 and FGFR4 are hyperphosphatemia and the blockade of bile acid synthesis, respectively." (PMID 27029060, 2016).
hypophosphatemia (1 paper, 2013). Lower than normal levels of phosphates in the circulating blood. "In a subsequent study, however, FGF23 did not reduce serum phosphorus levels in double Fgfr3/Fgfr4 KO mice, suggesting that FGFR3 and FGFR4 play redundant roles in phosphate regulation, and perhaps that FGFR1 activation is not sufficient for FGF23 to induce hypophosphatemia." (PMID 23451204, 2013).
hypothyroidism (1 paper, 2013). Abnormally low levels of thyroid hormone. "We found that hypothyroidism led to higher mRNA expression of Fgf-receptors relative to controls, leading to a delay in the down-regulation of Fgfr3." (PMID 23394545, 2013). "The observation of similar delays in the down-regulation of p75ntr and S100 proteins in differentiating cells in hypothyroid conditions is consistent with the idea that the maintenance of Fgfr3 signaling mediates at least some of the effects observed in hypothyroidism of the cochlea." (PMID 23394545, 2013). "Since hypothyroidism leads to a delay in down-regulation of Fgfr3, we hypothesized that there may be delays in the maturation of this epithelium." (PMID 23394545, 2013).
inflammatory breast carcinoma (1 paper, 2020). An advanced, invasive breast adenocarcinoma characterized by the presence of distinct changes in the overlying skin. "This has also been observed in inflammatory breast cancer, where 10 out of 156 (6.4%) cases had FGFR3 deletion." (PMID 31987043, 2020).
inflammatory skin disease (1 paper, 2020). Inflammatory skin disorders covers a broad category that includes many conditions ranging in severity, from mild itching to grave medical health complications These disorders are common in people of all ages and races. "However, the defect in the epidermal barrier and the resulting inflammatory skin disease that develops in mice lacking FGFR1 and FGFR2 in keratinocytes were further aggravated upon additional loss of FGFR3." (PMID 31830366, 2020).
influenza (1 paper, 2016). An acute viral infection of the respiratory tract, occurring in isolated cases, in epidemics, or in pandemics; it is caused by serologically different strains of viruses (influenzaviruses) designated A, B, and C, has a 3-day incubation period, and usually lasts for 3 to 10 days. "FGFR1 was shown to significantly impact cellular internalization of two influenza A viruses but FGFR3 was not expressed in the cell line tested, leaving open the possibility of its potential role in the influenza life cycle." (PMID 27403523, 2016).